EPO (erythropoietin)
Diseases named in the same sentence as EPO in open-access papers (continued):
Sharing a sentence is not in itself a finding about the gene and the disease.
anemia (continued). "EPO ranks among the costliest elements used in the treatment of anemia." (PMID 41012526, 2025). "Conversely, addressing anemia could reduce erythropoietin levels, a factor known to promote tumor progression and angiogenesis." (PMID 40592821, 2025). "FGF23 may aggravate anemia through direct mechanisms, such as suppressing erythropoietin secretion and inducing red blood cell apoptosis, and indirect mechanisms, including effects on iron metabolism via inflammatory cytokine induction." (PMID 41157262, 2025). "HbA1c becomes less reliable as kidney function deteriorates to stages 3 to 4, as its results may be influenced by anemia, erythropoietin medication, or other CKD-related variables." (PMID 41190245, 2025). "The process of eryptosis in AIHA can be modulated by erythropoietin, which not only stimulates erythropoiesis but might also inhibit eryptosis, thus improving anemia." (PMID 40592821, 2025). "Erythropoietin (EPO) is an FDA-approved drug for anemia, which may help in the treatment of PNCI by transdifferentiating resident SCs into repair SCs (rSCs) and enhancing phagocytosis to facilitate the removal of cellular debris." (PMID 40610400, 2025). "Elevated EPO levels represent the physiological response to anemia." (PMID 40574855, 2025). "Therefore, when anemia develops, ERFE production increases for two main reasons: first, EPO stimulation causes the pool of erythroid precursor cells to expand, and second, each of these precursors increases ERFE production." (PMID 41007630, 2025). "Chemotherapy also reduces EPO production, leading to a worsening of anemia." (PMID 40076818, 2025). "The higher rate of prior nephrectomy in the spRCC group may further contribute to anemia, given the kidney’s known role in EPO production." (PMID 40920370, 2025). "Finally, inflammatory cytokines such as interleukin-1 and tumor necrosis factor-α also contribute to final anemia by suppressing erythropoietin expression and increasing erythrocyte phagocytosis." (PMID 40718381, 2025). "Additionally, ER stress can impair erythropoiesis by suppressing erythropoietin production, thereby contributing to anemia." (PMID 40980042, 2025). "Erythropoietin Twenty to thirty per cent of people given recombinant human erythropoietin to correct anaemia in malignancies and end-stage renal disease may have hypertension induced or exacerbated within 2 to 16 weeks of starting treatment." (PMID 39653728, 2025). "Anemia of chronic renal disease as well as cancer and chemotherapy‐induced anemia (CIA) are often associated with poor outcomes, and the use of erythropoietin stimulating agents (ESAs) for patients with chronic kidney disease (CKD) and anemia associated with cancer has been a common practice." (PMID 41425520, 2025). "These therapeutic interventions do not address the causes of anemia but rather aim to compensate for the decreased level of erythropoietin or compensate for functional or absolute iron deficiency." (PMID 39860312, 2025). "Notably, EPO replacement therapy often results in fluctuating HgB levels, which represent a well-documented clinical challenge for nephrologists in balancing anemia." (PMID 40508930, 2025). "Anemia in DKD is predominantly attributed to deficiencies in iron and/or erythropoietin." (PMID 39958038, 2025). "Anemia is one of the common adverse reactions, especially in the first few weeks of the treatment and is related to the on-target effect on the HIF2α-target gene erythropoietin (EPO)." (PMID 40620865, 2025). "A lack of erythropoietin is not solely responsible for the underlying etiology of anemia of CKD; impaired iron metabolism and inflammation also play a role in the pathophysiology." (PMID 39860312, 2025). "Therefore, IS not only impairs EPO signaling but also interferes with erythroid maturation and survival, compounding the challenge of managing anemia and potentially blunting the beneficial cellular effects of ESAs in CKD." (PMID 41227308, 2025).
anemia (continued). "The plasma EPO level is disproportionate to the level of anemia." (PMID 40027896, 2025). "Age-related changes may impair organ functions, including erythropoietin production, which becomes insufficient to prevent anemia under certain conditions." (PMID 41294841, 2025). "Since erythropoiesis is impaired when the kidney is denervated due to reduced erythropoietin production in response to hypoxia, we also examined whether there were any clinical issues with treatment for anaemia." (PMID 40599628, 2025). "The authors recommend starting EPO as soon as possible after birth in infants with HS and early anemia as the reticulocyte count in the EPO-treated group was higher at 30 DOL than in the transfusion only group, whereas it was similar between the two groups at 180 DOL." (PMID 41007072, 2025). "Patients with advanced CKD who develop anemia and concomitant erythropoietin resistance may require erythropoiesis-stimulating agents, such as high-dose erythropoietin." (PMID 40243751, 2025). "In addition, tumour-related chronic inflammation can disrupt iron metabolism and alter erythropoietin (EPO) function, further exacerbating the cycle of anemia and bone marrow dysfunction." (PMID 41438123, 2025). "We and others could show that, for example, in anaemia or after pharmacological EPO induction, cortical fibroblasts can express both EPO and renin simultaneously." (PMID 40853869, 2025). "Similarly, recent blood transfusions can suppress reticulocyte production by alleviating anaemia and reducing erythropoietin stimulation." (PMID 40344013, 2025). "Treatment of preoperative anemia with iron and erythropoietin, and perioperative cellsalvage, reduced the need for blood transfusions and may improve patient outcomes." (PMID 40636174, 2025). "Patients on hemodialysis often develop anemia due to reduced erythropoietin production." (PMID 41583201, 2025). "To evaluate the function of EPO on anemia and renal protection, we generated a mouse anemia model based on kidney injury by cisplatin injection, and then tested the effect of recombinant mouse EPO administration." (PMID 41179707, 2025). "The occurrence of anemia in patients with hyperthyroidism is attributed to increased body metabolism resulting from excess thyroid hormones, tissue hypoxia, increased erythropoietin production by the kidneys that stimulates erythropoiesis, and an increased demand for iron, B12, and folate." (PMID 40963528, 2025). "In an early piece of work, EPO 40 000 U biweekly as induction therapy followed by 40 000 U weekly maintenance was demonstrated effective in rapidly correcting anaemia, improving quality of life (QoL) and reducing transfusion requirements in LR‐MDS patients with Hb <10 g/dL." (PMID 40318055, 2025). "Additionally, anemia from reduced erythropoietin production in CKD further strains the heart, potentially contributing to left ventricular hypertrophy and heart failure." (PMID 40711156, 2025). "Anemia is a common complication in cancer patients undergoing chemotherapy, often due to myelosuppression, where the bone marrow’s ability to produce blood cells is suppressed by cytotoxic agents, and reduced EPO production due to kidney damage." (PMID 40725749, 2025). "Regarding management of anemia 73 (33.9%) of the anemic subjects received blood transfusion, 14 (6.5%) received iron therapy, 20 (9.3%) of studied subjects were given erythropoietin, 3 (1.4%) of them were given vitamin B12 and 3 (1.4 %) were given folic acid as seen in." (PMID 40765547, 2025). "CKD patients frequently develop anemia due to reduced erythropoietin production, and elevated MCV may reflect a more severe form of anemia or underlying inflammation, both of which are known to be linked to higher mortality rates." (PMID 40802782, 2025). "GM-induced anemia may be ascribed to the decreased erythropoietin hormone and enhanced RBC fragility following GM treatment." (PMID 40313618, 2025).
anemia (continued). "Anemia (low hemoglobin) acts as both a risk factor for AKI (e.g., reduced oxygen-carrying capacity exacerbates renal injury during ischemia) and a consequence (e.g., decreased renal erythropoietin secretion), forming a bidirectional relationship." (PMID 40766058, 2025). "Anemia is a common and clinically significant complication observed in patients with chronic kidney disease (CKD), resulting from complex interactions between renal dysfunction, erythropoietin (EPO) deficiency, and altered iron metabolism." (PMID 40225399, 2025). "The treatment indications for the HMA were MDS with IPSS intermediate‐1 with anemia and no response to EPO or with another cytopenia, intermediate‐2, or high risk." (PMID 40124717, 2025). "Furthermore, diabetic patients are more likely to have iron deficiency due to impaired intestinal absorption, which further contributes to anemia, along with an impaired ability to produce erythropoietin in response to decreased hemoglobin." (PMID 40966829, 2025). "However, as the infection progresses and anemia develops, erythropoietic drive increases, leading to elevated EPO and subsequent production of erythroferrone (ERFE), which suppresses hepcidin." (PMID 40871363, 2025). "By intrarenal implantation of the injury‐responsive EPO‐producing (iREP) cells, functional EPO could be released into the kidney of injured mice to correct anemia and protect the kidney." (PMID 41179707, 2025). "Erythropoietin (EPO), although effective in correcting radiation anemia, may promote tumor angiogenesis through the vascular endothelial growth factor (VEGF) signaling pathway." (PMID 40688089, 2025). "However, as anaemia progresses, tissue hypoxia stimulates erythropoietin (EPO) and erythroferrone production—both known to suppress hepcidin." (PMID 40637365, 2025). "Many factors could contribute to anemia as CKD progresses, but impaired production of erythropoietin (EPO) due to kidney tissue injury is the central cause." (PMID 41179707, 2025). "Furthermore, the presence of CKD exacerbates the effects of anemia, as patients often exhibit lower hemoglobin levels due to decreased erythropoietin production and other factors related to kidney dysfunction." (PMID 40004701, 2025). "Several potential mechanisms may contribute to the development of anemia and EPO resistance in response to SARS-CoV-2." (PMID 40126283, 2025). "Additional therapies that may be considered alone or in combination with ruxolitinib for MF‐related anaemia include erythropoietin‐stimulating agents (ESAs), danazol and erythroid maturation agents." (PMID 40123795, 2025). "However, absolute erythropoietin levels are often difficult to interpret and are of limited value, especially in patients with anemia of chronic disease." (PMID 41303295, 2025). "Anemia management in this population is complex, particularly due to erythropoietin resistance, which may be exacerbated by COVID-19-related inflammation." (PMID 40126283, 2025). "Clinically relevant predictions based on the results of this study may include decisions regarding the use of soluble iron in combination with erythropoietin and vitamin B12 or transfusion of packed red blood cells (pRBCs) in patients with anemia." (PMID 39941007, 2025). "In β-thalassemia, chronic anemia and tissue hypoxia drive persistently elevated EPO levels." (PMID 41517557, 2025). "Physiological anemia is common in nearly all newborns during the first months of life and is more pronounced in very preterm infants, primarily due to their impaired ability to increase erythropoietin production in immature kidneys." (PMID 39857694, 2025). "Grade 3–4 anemia and neutropenia were managed with EPO and G-CSF, respectively." (PMID 40002670, 2025). "Interestingly, VIT treatment further increased the serum EPO levels in P. yoelii infected mice, supporting the presence of severe anemia and dyserythropoesis in VIT-treated infected group, consistent with our earlier findings." (PMID 40871363, 2025).
anemia (continued). "This difference may be explained by the exclusion of patients with severe anemia in some studies, local differences in nutritional and iron supplementation, and variable access to the erythropoietin therapy." (PMID 41216054, 2025). "Research suggests that UTUC may induce anemia by impairing the body’s ability to utilize iron, disrupting normal kidney function, and reducing erythropoietin production in the kidneys." (PMID 40842585, 2025). "LPI may also result in chronic microcytic normochromic anaemia, proposed to result at least in part from reduced erythropoietin (EPO) production." (PMID 41464651, 2025). "Also, the patient described longstanding anemia, lasting from the HD initiation, that was resistant to iron supplements and erythropoietin replacement aligned with several blood transfusions." (PMID 39758152, 2025). "Currently, researchers can genetically intervene with erythropoietin at the molecular level and better express the gene locus for anemia treatment, suggesting that rhEPO is effective for both surgery and cancer-related anemia." (PMID 41268443, 2025). "Impaired erythropoietin production leads to anemia in the end-stage of DN and CKD." (PMID 40471290, 2025). "Therefore, in the presence of increased inflammatory factors, the decrease in erythropoiesis due to reduced EPO promotes anemia." (PMID 40362375, 2025). "Moreover, erythropoietin-resistant anemia, which involves chronic inflammation in its pathogenesis, also shows a significant correlation with PLR." (PMID 41295836, 2025). "The impact of oxidative stress extends beyond the vasculature as recent studies have shown that excessive ROS impair hematopoietic stem cell renewal and differentiation, contributing to erythropoietin-resistant anemia and the immune dysfunction observed in uremic patients." (PMID 41516280, 2025). "Treatment protocol for anemia mostly follows a step-ladder approach, keeping in view the severity, but mostly requires initial treatment with oral or IV iron supplements, followed by subcutaneous erythropoietin." (PMID 41523403, 2025). "Targeting eryptosis—alongside optimizing EPO and iron therapy—may represent a novel strategy to improve anemia management in NDD-CKD, though further longitudinal studies are needed to confirm causality and identify actionable molecular targets." (PMID 41383483, 2025). "Diabetic nephropathy, primarily leads to anemia by reducing erythropoietin (EPO) secretion." (PMID 40034738, 2025). "Furthermore, anemia can result from proinflammatory cytokines disrupting iron homeostasis and EPO synthesis, both of which are essential for erythropoiesis." (PMID 40364122, 2025). "We have shown that iron availability plays an important role in mediating testosterone's effect on erythropoiesis and that in an iron-restricted mice, testosterone treatment worsens anemia because of ineffective erythropoiesis possibly due to erythropoietin resistance." (PMID 39911523, 2025). "This is important in chronic renal disease, where EPO is used to treat anemia." (PMID 41382083, 2025). "We therefore investigated whether HIF‐2 stabilization by anaemia or PHDi treatment would alter the number of EPO+ cells in PDGFR‐βCreERT2/+ PHD3ff mice compared to control animals." (PMID 40853869, 2025). "The chronic inflammatory state further induces anemia of chronic disease (ACD) through dual mechanisms: suppression of erythropoietin bioactivity and hepcidin-mediated sequestration of iron within macrophage stores, thereby creating functional iron deficiency in erythroid progenitor cells." (PMID 40687061, 2025). "Consequently, this dysregulation can lead to persistent anemia, a hallmark of CKD, stemming from a relative deficiency in EPO production, a key aspect of the pathophysiology of renal anemia." (PMID 38612557, 2024). "Additionally, the suppressed erythropoietin response to anemia hampers the body’s ability to stimulate red blood cell production in response to low hemoglobin levels." (PMID 38675885, 2024).
anemia (continued). "Moreover, it is significant to acknowledge that patients with CKD commonly experience lowered erythropoietin levels and exhibit heightened levels of prolactin, which ultimately leads to an increased incidence of anemia and decreased levels of hemoglobin." (PMID 38348104, 2024). "Finally, another possible mechanism by which anemia affects the bones is elevated blood erythropoietin (EPO) levels." (PMID 38323109, 2024). "EPO-induced Pure Red Cell Aplasia (PRCA) is a rare condition of profound anemia with EPO treatment." (PMID 38528249, 2024). "Notably, our patient’s anemia continued to improve despite having low follow-up levels of EPO upon discontinuation of aranesp." (PMID 39207555, 2024). "In contrast, in humans, EPO was found to be increased in subjects with obesity and anaemia." (PMID 38696124, 2024). "For instance, anaemia and EPO were over-represented in the mined corpus of publications." (PMID 39682316, 2024). "In four studies on CKD anemia, erythropoietin was used in all cases." (PMID 39338353, 2024). "The unique mechanism of HIF-PH inhibitors, which increases endogenous erythropoietin and addresses iron utilization dysfunction, may offer particular benefits for this population, given that these factors are primary contributors to anemia in heart failure." (PMID 39768541, 2024). "With or without demonstrable EPO Abs, our case showed that treatment with cyclosporine and a switch to Roxadustat might be proven and effective in treating this type of severe anemia in patients treated with EPO previously." (PMID 38528249, 2024). "Erythropoietin (EPO) was found the most commonly utilized drug to improve anemia in this study." (PMID 38658828, 2024). "Actually, the major cause of anemia in these patients is a lack of erythropoietin synthesis by failing kidneys." (PMID 38542300, 2024). "Our systematic review and network meta-analysis (NMA) mark a significant step forward in evaluating the efficacy of daprodustat across various doses, alongside recombinant human erythropoietin (rhEPO) and placebo, in treating anemia among dialysis-dependent chronic kidney disease (CKD) patients." (PMID 38828426, 2024). "SHPT is a major comorbidity with adverse health consequences on CKD progression when present in the earlier stages, as well as on the risk of vascular calcifications, major adverse cardiovascular events (MACE), erythropoietin-resistant anemia, fractures, and death." (PMID 38893652, 2024). "E. cuniculi is a major cause of renal failure in rabbits, leading to granulomatous and fibrotic lesions that might impair erythropoietin production and contribute to anemia." (PMID 39409715, 2024). "Finally, for the treatment of anemia, a PEGylated EPO and a PEGylated EPO derived peptide are under clinical investigation." (PMID 38193121, 2024). "In inflammatory states, the EPO secretion in response to anemia is blunted." (PMID 39591250, 2024). "Thesefactors may be the cause of increased cardiovascular risk and all-cause death.Fifth, studies indicated that the use of angiotensin-converting enzyme (ACE) inhibitors can depress the synthesisof erythropoietin, which can aggravate anemia." (PMID 39077655, 2024). "However, both anemia and neutropenia can be well managed with supportive care, including the use of erythropoietin or G-CSF." (PMID 38916742, 2024). "The proof-of-principle for this hypothesis had already been obtained in 1984 by experiments demonstrating that EPO-rich plasma cures anemia in a sheep model of chronic renal failure." (PMID 38672425, 2024). "Anemia due to chronic kidney disease (CKD) is characterized by inadequate levels of erythropoietin (EPO) and leads to cardiovascular dysfunction, reduced physical activity, and impairs quality of life, and is associated with increased hospitalization and mortality rates in both adults and children." (PMID 37566114, 2024). "Anemia parameters and EPO levels were also found to be comparable between the two groups." (PMID 39597967, 2024).